NPRL2 (NPR2 like, GATOR1 complex subunit)
Description:
Catalytic component of the GATOR1 complex, a multiprotein complex that functions as an inhibitor of the amino acid-sensing branch of the mTORC1 pathway. In response to amino acid depletion, the GATOR1 complex has GTPase activating protein (GAP) activity and strongly increases GTP hydrolysis by RagA/RRAGA (or RagB/RRAGB) within heterodimeric Rag complexes, thereby turning them into their inactive GDP-bound form, releasing mTORC1 from lysosomal surface and inhibiting mTORC1 signaling. In the presence of abundant amino acids, the GATOR1 complex is ubiquitinated and inhibited by GATOR2. Within the GATOR1 complex, NPRL2 constitutes the catalytic subunit that mediates the GTPase activator activity and under methionine-sufficient conditions, the GTPase activator activity is inhibited by PRMT1 through methylation and consequently inducing timely mTORC1 activation. Suppresses Src-dependent tyrosine phosphorylation and activation of PDPK1 and its downstream signaling. Down-regulates PDPK1 kinase activity by interfering with tyrosine phosphorylation at 'Tyr-9', 'Tyr-373' and 'Tyr-376' residues. May act as a tumor suppressor. Suppresses cell growth and enhances sensitivity to various anticancer drugs.
Synonyms: TUSC4; NPR2L; NPR2; FFEVF2
Tractability: Small molecule: a structure with a bound ligand is known. PROTAC: UniProt records ubiquitination sites on it; ubiquitination databases record sites on it; its protein half-life has been measured.
Gene: Protein-coding gene on chromosome 3 (50,347,330 to 50,350,826, reverse strand). Ensembl gene ENSG00000114388.
Subcellular location: Lysosome membrane
Pathways (Reactome):
Cellular responses to stimuli: Amino acids regulate mTORC1
Gene Ontology:
Molecular function: GTPase activator activity; protein binding
Biological process: cellular response to amino acid starvation; negative regulation of kinase activity; negative regulation of TORC1 signaling
Cellular component: GATOR1 complex; lysosomal membrane; vacuolar membrane
Genetic constraint (gnomAD): Loss-of-function variants: 21 observed, 53.64 expected, observed/expected ratio (o/e) 0.39, 90% interval 0.28 to 0.56. The upper end of that interval is the gene's LOEUF score, 0.56, which puts it in group 2 of 6, group 1 being the genes least tolerant of losing a copy. Missense variants: 376 observed, 503.46 expected, observed/expected ratio (o/e) 0.75, 90% interval 0.69 to 0.81. Synonymous variants: 175 observed, 195.98 expected, observed/expected ratio (o/e) 0.89, 90% interval 0.79 to 1.01.
Gene-disease validity (ClinGen):
ClinGen rates the evidence that NPRL2 causes each of these diseases.
focal epilepsy (autosomal dominant): Definitive. A seizure caused by a localized disorder.
Homologues: Orthologues: chimpanzee NPRL2 (99% identical), dog NPRL2 (98% identical), mouse Nprl2 (98% identical), rat Nprl2 (98% identical), guinea pig NPRL2 (98% identical), rabbit NPRL2 (98% identical), pig NPRL2 (92% identical), macaque NPRL2 (87% identical), zebrafish nprl2 (82% identical), tropical clawed frog nprl2 (81% identical), Drosophila melanogaster Nprl2 (45% identical), Caenorhabditis elegans nprl-2 (28% identical).
Diseases named in the same sentence as NPRL2 in open-access papers:
NPRL2 is named in the same sentence as 47 diseases in open-access papers, as found by Europe PMC text mining. Sharing a sentence is not in itself a finding about the gene and the disease. The quoted sentences say what the papers report.
lung carcinoma (17 papers, 2007 to 2025). "We previously reported that low expression of NPRL2 in distinct types of lung cancers was associated with cisplatin resistance and restoration of NPRL2 in NPRL2 deficient cells overcomes cisplatin resistance through the activation of the DNA damage checkpoint pathway." (PMID 39932765, 2025). "Although the function of NPRL2/G21 is still unknown, it revealed interesting association in lung cancer: gene decreased expression was conversely correlated with cisplatin sensitivity in NSCLC cell lines." (PMID 26112163, 2015). "Therefore, NPRL2/G21 deserves attention and further study in lung cancers, regarding its expression and underlying mechanisms of its possible silencing." (PMID 26112163, 2015). "At the same time, several genes downregulated in NPRL2−/− cells are also known to be downregulated in lung cancer (FBLN2, LBH, AMPH-1), glioblastoma (ELAVL2), and liver cancer (IGFBP4)." (PMID 41469472, 2025). "The downregulation of NPRL2 and its correlation with cisplatin resistance in lung cancer was initially reported almost two decades ago, before it was discovered that NPRL2 belongs to the GATOR1 complex." (PMID 41469472, 2025). "It was also shown that transgenic NPRL2 expression suppresses lung cancer cell proliferation in vitro by inducing apoptosis and cell cycle arrest in vitro, and it attenuates tumor xenograft formation in mice." (PMID 38915098, 2024). "Low expression of NPRL2 in different types of lung cancers was correlated with resistance to cisplatin, one of the primary chemotherapeutics for lung cancer." (PMID 29127423, 2017). "Further, reintroduction of NPRL2 into these cells inhibits cell proliferation both in cell lines and in human lung cancer mouse models." (PMID 19521502, 2009). "NPRL2 also induced strong apoptosis in another anti-PD1 resistant mouse lung cancer LLC2 cells." (PMID 39932765, 2025). "Furthermore, some reports have shown that NPRL2 gene or protein expression is high in some lung cancer tissues or cell lines." (PMID 38915098, 2024). "In addition, NPRL2 gene expression level is inversely correlated with cisplatin sensitivity in lung cancer cell lines, and NPRL2 overexpression inhibits cell growth and enhances sensitivity to cisplatin in lung cancer cell lines." (PMID 38915098, 2024). "Thus, it is critical to understand the complex mechanisms by which NPRL2 might affect lung cancer development." (PMID 38915098, 2024). "However, the expression of NPRL2 is slightly and significantly increased in lung cancer tissues compared to macroscopically unchanged lung tissues surrounding the primary lesion, making it unclear whether NPRL2 consistently acts as a tumor suppressor." (PMID 38915098, 2024). "FUS1, NPRL2/G21 and RASSF1A are TSGs from LUCA region at 3p21.3, a critical chromosomal region in lung cancer development." (PMID 26112163, 2015). "Three bona fide lung cancer tumor suppressor genes namely RBSP3 (AP20 region),NPRL2 and RASSF1A (LUCA region) were identified in the 3p21.3 region." (PMID 20193080, 2010). "Previously, we showed that restoration of NPRL2 in NPRL2-negative and cisplatin-resistant cells resensitize lung cancer cells to cisplatin treatment in vitro and in vivo." (PMID 20700484, 2010). "In this study, we showed that exogenous NPRL2 expression in NPRL2-negative tumor cells activated the DNA damage pathway, as evidenced by activation of ATM and NBS1 and increased γ-H2AX expression in lung cancer cells after NPRL2 treatment." (PMID 20700484, 2010). "Expression of HYAL1 and HYAL2 was almost undetectable in the KRC/Y renal and U2020 lung carcinoma lines (data not shown), which were used in our growth suppression experiments for testing RASSF1A and G21/NPRL2." (PMID 18725949, 2008).
epilepsy (16 papers, 2019 to 2025). A brain disorder characterized by episodes of abnormally increased neuronal discharge resulting in transient episodes of sensory or motor neurological dysfunction, or psychic dysfunction. "Herein, we show the functional effect of epilepsy-linked human mutations in the NPRL2 subunit of GATOR1 on mTORC1-dependent signal transduction." (PMID 38396745, 2024). "Herein, we report that epilepsy-linked mutations in the NPRL2 subunit of GATOR1, NPRL2-L105P, -T110S, and -D214H, increase basal mTORC1 signal transduction in cells." (PMID 38396745, 2024). "The expansive number of GATOR1 mutations linked with epilepsy in humans prompted us to investigate the biochemical function of individual NPRL2 mutants and determine their contribution to mTORC1 signal transduction." (PMID 38396745, 2024). "Collectively, our results show that epilepsy-linked mutations in NPRL2 can block GATOR1 complex assembly and restrict the appropriate regulation of mTORC1 by canonical PI3K-dependent growth factor signaling in the presence or absence of amino acids." (PMID 38396745, 2024). "We conclude that NPRL2 functions as an important regulator of mTORC1 activity that controls the expression of epilepsy-linked Scn1A expression to regulate the strength of neuronal APs." (PMID 35165201, 2022). "Human mutations in NPRL2 are associated with a spectrum of neurologic disorders, including autism, epilepsy, and SUDEP." (PMID 35165201, 2022). "The increased AP strength is consistent with elevated expression of epilepsy-linked, voltage-gated sodium channels in the NPRL2-deficient brain." (PMID 35165201, 2022). "Intriguingly, animal studies have shown that dopamine levels are decreased in rat models expressing epilepsy linked Scn1A mutations, providing a functional link between the overexpression of Scn1A and reduced dopamine levels in the NPRL2 nKO model." (PMID 35165201, 2022). "The chromosome 3 region spans 159 genes, including neuronal development genes SEMA3F and SEMA3B, and epilepsy-associated genes NPRL2, CACNA2D2, and CYB561D2." (PMID 35190550, 2022). "The results of literature review showed that there were a total of 20 patients with NPRL2-related epilepsy whose mutations were mostly missense and hereditary." (PMID 34912289, 2021). "DEPDC5 mutations account for 83% of all GATOR1-related epilepsies, while the remaining 17% is made up of NPRL2 (6%) and NPLR3 (11%) variants." (PMID 34632383, 2021). "To date, 11 variants in the NPRL2 gene have been described in 14 epilepsy probands." (PMID 34376795, 2022). "In addition, loss of NPRL2 increases the strength of electrically stimulated action potentials (APs) and the expression of epilepsy-linked sodium channels." (PMID 35165201, 2022). "Mutations in NPRL2 are associated with familial forms of epilepsy." (PMID 35165201, 2022). "Nitrogen permease regulator-like 2 (NPRL2) is a requisite subunit of the epilepsy-linked GAP activity toward Rags 1 (GATOR1) complex that functions as a negative regulator of mammalian target of rapamycin complex 1 (mTORC1) kinase when intracellular amino acids are limited." (PMID 35165201, 2022). "Nprl2 and Nprl3 mutation are less frequent (6% and 9%, respectively), which might be partially related with the fact that their involvement in epilepsies and brain malformations has been tested in a low number of people." (PMID 34685669, 2021). "NPRL3‐related epilepsy is slightly more common among females and a similar gender disparity was reported in the prevalence of DEPDC5 and NPRL2‐related epilepsy." (PMID 37491868, 2023). "A total of 33 children underwent preoperative genetic whole‐exome testing, and 4 of them had pathogenic genes related to epilepsy, including CACNA1A, CREBBP, MTOR, and NPRL2." (PMID 37786975, 2023). "These metabolic links to epilepsy prompted us to investigate the role of NPRL2 in glutamatergic neurons, which use glutamate as an excitatory neurotransmitter." (PMID 35165201, 2022).
epilepsy (continued). "Here, we show that loss of NPRL2 expression in mouse excitatory glutamatergic neurons causes seizures before death, consistent with SUDEP in humans with epilepsy." (PMID 35165201, 2022). "Here, we presented two clinical cases with NPRL2-related epilepsy, and discussed the characteristics, diagnosis, and treatment processes in the context of existing literature." (PMID 34912289, 2021). "Because somatic variants in GATOR1-encoding genes (>400 in DEPDC5, >80 in NPRL2, and >100 in NPRL3 in the COSMIC database) have been mentioned in various cancers, we examined cancer occurrence in epilepsy probands carrying germline GATOR1 variants." (PMID 30093711, 2019). "We assembled a cohort of 73 previously unreported probands with rare variants in DEPDC5, NPRL2, and NPRL3 through international networking with diagnostic epilepsy centers." (PMID 30093711, 2019). "In fact, loss-of-function mutations in GATOR1 genes such as DEPDC5, NPRL2, and NPRL3) have been frequently associated with malformations of cortical development leading to focal, drug-resistant epilepsy with fair risks of sudden unexpected death in epilepsy (SUDEP)." (PMID 36639812, 2023). "GATOR1-related epilepsies caused by DEPDC5, NPRL2, and NPRL3 variations exhibit various phenotypes consisting of sleep-related focal hypermotor seizures, infantile spasms, and other focal epilepsies, including frontal, temporal, occipital, parietal, centrotemporal epilepsies." (PMID 34376795, 2022). "The more recent discovery of epilepsy-causative NPRL2 and NPRL3 variants and the greater length of the DEPDC5 transcript (5551 bp) compared with NPRL2 (1700 bp) and NPRL3 (2881 bp) have been offered as explanations for the increased frequency of DEPDC5-associated epilepsies." (PMID 34632383, 2021). "This study aimed to explore the phenotype and genotype spectrum of NPRL2-related epilepsy." (PMID 34912289, 2021). "It is thought that the hyperactivation of mTOR pathway, as seen in other disorders such as sclerosis tuberous, PTEN, and GATOR1 complex deficiency (including DEPDC, NPRL2, and NPRL3 deficiencies), may cause epilepsy through the alteration of normal neural networks." (PMID 36003298, 2022). "As genetic studies have identified >700 mutations in genes that code for voltage-gated sodium channels in epilepsy, and reports of GATOR1 and Scn1A mutations contributing to temporal epilepsy, our data now implicate the NPRL2 and mTORC1 regulatory pathways in controlling Scn1a expression." (PMID 35165201, 2022). "Similarly, the higher recurrence of NPRL2 mutations in cancers and DEPDC5 mutations in epilepsies could be related with the specific moonlighting functions of these GATOR1 members beyond the regulation of the mTORC1 pathway." (PMID 34685669, 2021). "Such a favorable surgery outcome, already described in GATORopathies (DEPDC5‐, NPRL2‐, and NPRL3‐related epilepsy), stands in favor of the presurgical sequencing of GATOR1 genes in subjects with either non‐lesional or FCD‐like imaging patterns." (PMID 37491868, 2023). "In striking contrast to other GATOR1 components, and especially to its paralogue NPRL2, NPRL3 seems to be less important for epilepsy and cancer." (PMID 34685669, 2021).
focal epilepsies (12 papers, 2019 to 2025). "Overall, germline variants in the GATOR1 complex genes (DEPDC5, NPRL3, and NPRL2) are present in ~10% of focal epilepsy cases, which can be familial or sporadic, especially in familial focal epilepsy with variable foci (FFEVF)." (PMID 34376795, 2022). "Limited studies have suggested that variants of NPRL2 are correlated with focal epilepsy, which may be associated with focal cortical dysplasia (FCD) and intellectual disability." (PMID 34376795, 2022). "Among the etiologies of focal epilepsy, mutations of the GATOR1 complex genes—comprising NPRL3, NPRL2, and DEPDC5—are known to result in overactivation of mTORC1." (PMID 40971258, 2025). "Mutations in GATOR1-RagA/B-mTORC1 pathway-related genes (DEPDC5, NPRL2, and NPRL3) have been reported in over 180 families with focal epilepsy, with DEPDC5 mutations being the most common, accounting for 85% of all cases." (PMID 38966089, 2024). "In 2016, mutations related with focal epilepsies, familial cortical dysplasia and SUDEP were also reported for Nprl2 and Nprl3." (PMID 34685669, 2021). "Further analysis revealed that FEFS + /FS had a lower frequency of null mutation than MCD or other focal epilepsies; and missense mutations associated with FEFS + /FS were located away from the binding sites to NPRL2/NPRL3 or RAGA/RAGC." (PMID 32848577, 2020). "With over 180 unrelated families described to date, genes of the GATOR1-mTORC1 pathway (DEPDC5, NPRL2, and NPRL3) are collectively the most frequently mutated genes in focal epilepsies, among which DEPDC5 is predominantly found (85% of all cases)." (PMID 30093711, 2019). "Genetic mutations in nitrogen permease regulator-like 2 (NPRL2) are associated with a wide spectrum of familial focal epilepsies, autism, and sudden unexpected death of epileptics (SUDEP), but the mechanisms by which NPRL2 contributes to these effects are not well known." (PMID 35165201, 2022). "Recent studies have linked mutations in several genes involved in the mTOR signaling pathway - such as TSC1, TSC2, MTOR, DEPDC5, NPRL2, and NPRL3 - to the development of focal epilepsies in affected individuals." (PMID 40546503, 2025). "Pathogenic or likely pathogenic variants in the DEPDC5, NPRL2 and NPRL3 genes were identified in 8–11% of individuals within focal epilepsy cohorts, mostly comprised of familial non-lesional cases." (PMID 34632383, 2021).
non-small cell lung carcinoma (7 papers, 2010 to 2025). A group of at least three distinct histological types of lung cancer, including non-small cell squamous cell carcinoma, adenocarcinoma, and large cell carcinoma. "Reduced expression of NPRL2 in non-small cell lung cancer (NSCLC) and its restoration caused inhibition of colony formation and apoptosis induction." (PMID 39932765, 2025). "A correlation between low expression of NPRL2 and cisplatin resistance has been previously reported for various non-small-cell lung cancer cell lines." (PMID 41469472, 2025). "In this study, we show that sensitization of non-small cell lung cancer (NSCLC) cells to cisplatin by NPRL2 is accomplished through the regulation of key components in the DNA-damage checkpoint pathway." (PMID 20700484, 2010). "NPRL2 plays an important role in cisplatin-induced resistance in human non-small-cell lung cancer cells." (PMID 20193080, 2010). "Therefore, we hypothesized that the sensitization of non-small cell lung cancer (NSCLC) cells to cisplatin by NPRL2 may be due to the direct regulation of key components in the DNA-damage checkpoint pathway." (PMID 20700484, 2010). "To investigate this further we chose RBSP3, NPRL2 and RASSF1A and analyzed their expression by qPCR in primary tumors: non-small cell lung cancer (NSCLC) - adenocarcinoma (AC) and squamous cell lung cancer (SCC)." (PMID 20193080, 2010). "The pre-specified hypothesis tested in the study was that the expression levels of 3 selected TSGs from LUCA region (FUS1, NPRL2/G21 and RASSF1A) were decreased in primary non-small cell lung cancer with promoter hypermethylation as the responsible epigenetic mechanism of their silencing." (PMID 26112163, 2015).
glioblastoma (4 papers, 2016 to 2025). The most malignant astrocytic tumor (WHO grade IV). "Inactivating mutations in GATOR1 components DEPDC5 and NPRL2 have also been identified in glioblastomas and ovarian cancers, and reduced expression of NPRL2 has been detected in a number of other cancers." (PMID 27462445, 2016).